WFDC11 (WAP four-disulfide core domain 11)
Synonyms: WAP11
Tractability: Antibody: UniProt places it where antibodies can reach, with high confidence; UniProt predicts a signal peptide or a membrane-spanning region; its Gene Ontology location is reachable by antibodies, with medium confidence.
Gene: Protein-coding gene on chromosome 20 (45,648,563 to 45,670,270, reverse strand). Ensembl gene ENSG00000180083.
Subcellular location: Secreted
Gene Ontology:
Molecular function: serine-type endopeptidase inhibitor activity
Biological process: antibacterial humoral response; innate immune response
Cellular component: extracellular region
Genetic constraint (gnomAD): Loss-of-function variants: 9 observed, 10.88 expected, observed/expected ratio (o/e) 0.83, 90% interval 0.5 to 1.44. The upper end of that interval is the gene's LOEUF score, 1.44, which puts it in group 5 of 6, group 1 being the genes least tolerant of losing a copy. Missense variants: 106 observed, 107.5 expected, observed/expected ratio (o/e) 0.99, 90% interval 0.84 to 1.16. Synonymous variants: 32 observed, 35.32 expected, observed/expected ratio (o/e) 0.91, 90% interval 0.68 to 1.22.
Homologues: Orthologues: chimpanzee WFDC11 (92% identical), macaque WFDC11 (89% identical), rabbit WFDC11 (55% identical), mouse Wfdc11 (45% identical), rat Wfdc11 (45% identical), Drosophila melanogaster CG5639 (16% identical), Caenorhabditis elegans C08G9.2 (14% identical). Paralogues in human: WFDC9 (39% identical), WFDC10B (25% identical), WFDC10A (24% identical), WFDC13 (21% identical), PI3 (18% identical), SLPI (17% identical), WFDC5 (17% identical), WFDC3 (16% identical), WFDC12 (13% identical).
Diseases named in the same sentence as WFDC11 in open-access papers:
WFDC11 is named in the same sentence as 3 diseases in open-access papers, as found by Europe PMC text mining. Sharing a sentence is not in itself a finding about the gene and the disease. The quoted sentences say what the papers report.
psychological distress (1 paper, 2019). "The linkage disequilibrium block (LDB) to which the top-hit SNP belongs contains a few genes, including WFDC11, 10B, and 9, and we cannot identify the causal gene(s) for psychological distress." (PMID 30705256, 2019).
WFDC11 also shares sentences with these, for which no sentence is quoted: metastatic melanoma (1 paper); metastatic tumors (1).